CTTN (cortactin)
Diseases named in the same sentence as CTTN in open-access papers (continued):
Sharing a sentence is not in itself a finding about the gene and the disease.
non-Hodgkin B-cell lymphomas (2 papers, 2021 to 2023). "In addition; high cortactin expression has been proposed as a diagnostic marker for non-Hodgkin B-cell lymphomas." (PMID 33773540, 2021). "In recent research, the expression of cortactin was examined in 131 occurrences of non-Hodgkin B-cell lymphomas and leukemias." (PMID 38179383, 2023).
papillary thyroid cancer (2 papers, 2016 to 2024). "We therefore further evaluated CTTN and PBF expression in papillary thyroid cancer (PTC) by RNA-seq (TCGA)." (PMID 27603901, 2016). "Stratification of papillary thyroid cancer (THCA) TCGA expression data using quartile values (Q3Q4 vs Q1Q2) further highlighted the potential clinical relevance for 5 of these NIS interactors (AP2A2, ARF6, CTTN, HLA-A and RAB5C) on disease recurrence following RAI treatment (P < 0.05)." (PMID 37921808, 2024).
Parkinson disease (2 papers, 2021 to 2022). A progressive degenerative disorder of the central nervous system characterized by loss of dopamine producing neurons in the substantia nigra and the presence of Lewy bodies in the substantia nigra and locus coeruleus. "Interestingly, the study identified CTTN as a key regulator involved in the clearance of impaired mitochondria, a major process associated with suppression of Parkinsonism." (PMID 36518382, 2022).
Sepsis (2 papers, 2022 to 2024). Sepsis is defined as life-threatening organ dysfunction caused by a dysregulated host response to infection. "Accordingly, we confirmed that CLP sepsis caused massive neutrophil infiltration into lungs and bronchoalveolar space in septic WT mice, a phenotype that was significantly reduced in septic cortactin-deficient mice." (PMID 35625756, 2022). "In our study, we show that the cytokine storm was significantly attenuated in cortactin-deficient mice during polymicrobial CLP sepsis." (PMID 35625756, 2022). "CLP sepsis caused massive neutrophil recruitment to the lungs in WT mice (49.1 ± 1.9%), which was significantly reduced in the lungs of septic CTTN KO mice (29.9 ± 1.7%)." (PMID 35625756, 2022). "CLP sepsis caused decreased levels of total peripheral blood leukocytes in septic WT and CTTN KO mice." (PMID 35625756, 2022). "Using a mouse model of CLP sepsis, we showed that cortactin deficiency improved survival in septic mice by attenuating the inflammatory response and reducing neutrophil infiltration that together prevented lung tissue damage." (PMID 35625756, 2022). "In summary, our study shows that cortactin deficiency is protective during murine sepsis by ameliorating the exaggerated inflammatory response and preventing neutrophil-inflicted tissue damage." (PMID 35625756, 2022). "The deficiency of cortactin improved histopathological changes occurring in the lung tissue during sepsis and, in line with our previous observation that cortactin-deficient mice have defects in neutrophil recruitment, we observed little neutrophil infiltration into septic lungs." (PMID 35625756, 2022). "Overall, cortactin deficiency attenuates the inflammatory response during CLP sepsis." (PMID 35625756, 2022). "Therefore, we hypothesised that cortactin deficiency improves the outcome of sepsis by limiting the recruitment of neutrophils into the lung, thus preventing organ damage associated with excessive neutrophil recruitment." (PMID 35625756, 2022). "Thus, cortactin deficiency exerts a protective effect on mice subjected to CLP sepsis." (PMID 35625756, 2022). "Moreover, other haematological parameters during sepsis were analysed in cortactin-deficient mice." (PMID 35625756, 2022). "Thus, cortactin deficiency also attenuates the systemic inflammatory response during sepsis." (PMID 35625756, 2022). "By contrast, plasma levels of IL-1β showed a significant increase during CLP sepsis in both WT and CTTN KO mice." (PMID 35625756, 2022). "Our findings highlight a critical role of cortactin for lung neutrophil infiltration and sepsis severity." (PMID 35625756, 2022). "Having observed fewer neutrophils in the lungs of septic CTTN KO mice compared to septic WT mice, the oxidative stress in the lungs during sepsis was analysed." (PMID 35625756, 2022). "While CLP sepsis significantly increased neutrophil numbers in the peritoneum of WT mice ((1.4 ± 0.1) × 106 cells/mL), peritoneal neutrophil numbers in septic CTTN KO mice were significantly lower ((0.5 ± 0.1) × 106 cells/mL) compared to septic WT mice." (PMID 35625756, 2022). "Using a murine model of sepsis induced by cecal ligation and puncture (CLP), we showed that cortactin-deficient (KO) mice survive better due to reduced lung injury." (PMID 35625756, 2022). "Given the reduced signs of inflammation and lesser lung injury in septic CTTN KO mice, the mRNA levels of inflammatory mediators in the lungs after sepsis were determined using quantitative real-time RT-PCR." (PMID 35625756, 2022). "In contrast, CTTN KO mice subjected to CLP sepsis showed a much better preserved lung tissue histology similar to the sham controls." (PMID 35625756, 2022). "We therefore hypothesised that cortactin plays a crucial role in sepsis development by regulating neutrophil trafficking." (PMID 35625756, 2022).
Sepsis (continued). "We conclude that reduced pulmonary neutrophil influx in amounts sufficient to control the infection but insufficient to cause tissue damage during sepsis constitutes the underlying mechanism explaining the improved survival of mice lacking cortactin." (PMID 35625756, 2022). "Due to the role of cortactin in supporting ICAM-1 functions to promote neutrophil extravasation, we hypothesised that cortactin promotes sepsis severity by supporting neutrophil influx into organs." (PMID 35625756, 2022). "In this study, we investigated whether the ABP cortactin, known to support neutrophil extravasation across the endothelial barrier, plays an important role in sepsis pathogenesis." (PMID 35625756, 2022). "Together, it is reasonable to conclude that the protective effect of cortactin deficiency during sepsis is not linked to haematological differences other than the differences in neutrophil recruitment patterns." (PMID 35625756, 2022). "Thus, differences in peripheral blood bacteria cannot explain the different sepsis outcome in WT and CTTN KO mice." (PMID 35625756, 2022). "Thus, except for neutrophil numbers, cortactin deficiency did not alter haematological parameters during sepsis." (PMID 35625756, 2022). "In other words, our finding that cortactin deficiency did not provide any additional protective effect on top of neutrophil depletion proves that the protective effects of cortactin deficiency during sepsis are owing to its inhibition of neutrophil recruitment." (PMID 35625756, 2022). "Indeed, sepsis led to increased expression of ICAM-1, VCAM-1 and P-selectin in WT mice with reduced expression of these adhesion molecules in septic CTTN KO mice comparable to sham controls." (PMID 35625756, 2022). "It is interesting as to why the absence of cortactin, an ABP required for the maintenance of the endothelial barrier via the activation of the small GTPase Rap1, did not exacerbate lung pathology during sepsis." (PMID 35625756, 2022).
sickle cell disease (2 papers, 2024). Sickle cell anemias are chronic hemolytic diseases that may induce three types of acute accidents: severe anemia, severe bacterial infections, and ischemic vasoocclusive accidents (VOA) caused by sickle-shaped red blood cells obstructing small blood vessels and capillaries. "In another hemin- induced ALI model with sickle cell disease, cortactin loss protects against hemin-induced ALI." (PMID 39162263, 2024). "We demonstrated that LPS, excessive mechanical stress, cytokines, hypoxia-inducible factors, antioxidant transcription factors, DNA demethylation, and a CTTN SNP, identified in a GWAS of a sickle cell disease cohort, each significantly influence CTTN promoter activity." (PMID 39162263, 2024).
T-cell acute lymphoblastic leukemia (2 papers, 2017 to 2023). Acute lymphoblastic leukemia of T-cell origin. "Moreover, cortactin is overexpressed in B cells of chronic lymphoblastic leukemia patients (CLL), implicated in T cell acute lymphoblastic leukemia (T-ALL), and promotes migration in cancer." (PMID 37485352, 2023).
thyroid cancer (2 papers, 2016 to 2020). "PBF and cortactin (CTTN) expression was determined in differentiated thyroid cancer and The Cancer Genome Atlas RNA-seq data." (PMID 27603901, 2016). "Together our results demonstrate that CTTN is overexpressed in thyroid cancer, particularly in the most aggressive forms, and significantly correlates with PBF expression." (PMID 27603901, 2016). "Importantly, we found that CTTN is over-expressed in differentiated thyroid cancer, particularly in patients with regional lymph node metastasis, which significantly correlates with elevated PBF expression." (PMID 27603901, 2016). "Given the interaction between CTTN and PBF, as well as significant correlations in thyroid cancer, we next depleted CTTN to determine the dependence of PBF on CTTN to promote cellular invasion." (PMID 27603901, 2016). "We conducted mass spectrometry in thyroid cancer cells to map the full range of interactions with PBF and identified CTTN as our top hit." (PMID 27603901, 2016).
acral melanoma (1 paper, 2022). "FER is also involved in cell-cell adhesion through phosphorylating proteins such as CTTN and β-catenin but FER amplification was not inversely correlated (P = 1) with CTTN amplification, a recurrent alteration in acral melanoma." (PMID 35706047, 2022).
ameloblastoma (1 paper, 2025). The most common odontogenic tumor, arising from the epithelial component of the embryonic tooth and usually affecting the molar-ramus region of the mandible or maxilla. "The aim of this study was to verify whether the expression of proteins related to the formation of invadopodia, MT1-MMP, cortactin, Tks-4 and Tks-5 is associated with the degree of tumor invasiveness of different types of unicystic ameloblastomas." (PMID 39941035, 2025). "In this study, the hypothesis was raised that MUA has higher expression of invadopodia-forming proteins, MT1-MMP, cortactin, Tks-4, and Tks-5, when compared to other subtypes of unicystic ameloblastoma, due to the location of neoplastic cells being present in the cystic capsule." (PMID 39941035, 2025). "Conventional ameloblastoma exhibited lower MT1-MMP, cortactin, and Tks-5 expression compared to MUA." (PMID 39941035, 2025). "Mural unicystic ameloblastoma (MUA) showed higher MT1-MMP, cortactin, Tks-4, and Tks-5 immunoexpression than luminal and intra-luminal types." (PMID 39941035, 2025). "Thus, this study aims to investigate the expression of Tks-4, Tks-5, cortactin and MT1-MMP proteins in the different histological subtypes of unicystic ameloblastomas and correlate it with the specific biological behavior of each subtype." (PMID 39941035, 2025).
Arrhythmia (1 paper, 2024). Any cardiac rhythm other than the normal sinus rhythm. "Decreased expression of CTTN leads to arrhythmias in mice, so it may inhibit the potassium ion channel Kv1.5 in LQT7 patients for prolonging the APD and QT intervals to aggravate the clinical symptoms." (PMID 38528561, 2024).
atherosclerosis (1 paper, 2022). A disease characterized by the build-up of fatty material and calcium deposition in the arterial wall resulting in partial or complete occlusion of the arterial lumen. "Further research results show that the RAB5A, CTTN, ITGB11and MMP9 can be used to predict atherosclerosis which is verified by GSE28829 and GSE43292." (PMID 35059464, 2022).
autism (1 paper, 2019). Persistent deficits in social interaction and communication and interaction as well as a markedly restricted repertoire of activity and interest as well as repetitive patterns of behavior. "In the present study, we show that DIP2A, coded by the autism candidate gene DIP2A, interacts with cortactin, which is essential for DIP2A-mediated acetylation of cortactin." (PMID 31600191, 2019).
carcinoma in situ of the esophagus (1 paper, 2015). "Cortactin is overexpressed in premalignant lesions, early stage dysplasia, and carcinoma in situ of the esophagus; together with Fascin and Survivin, high protein expression levels of Cortactin have been shown to be associated with worse prognosis of patients with ESCC." (PMID 26345720, 2015).
cardiac hypertrophy (1 paper, 2025). "The focus of this study is to elucidate the mechanism by which RBMS1 participates in myocardial hypertrophy through CTTN splicing variant in cardiomyocytes." (PMID 41214391, 2025). "We found that cardiomyocyte-specific deficiency of CTTN-Δe11 attenuated pathological cardiac hypertrophy by increasing sarcomere length and promoting aligned orientation of sarcomeres both in vivo and in vitro." (PMID 41214391, 2025). "Our results imply that the upregulation of the PI3K/AKT pathway by RBMS1 and CTTN-Δe11 is a pathogenic factor in cardiac hypertrophy." (PMID 41214391, 2025). "Altogether, the results show that RBMS1 activates the PI3K/AKT pathway via splicing CTTN to promote sarcomere chaos and cardiac hypertrophy." (PMID 41214391, 2025). "Taken together, these findings suggest that inhibition of CTTN-Δe11 mitigates cardiac hypertrophy via safeguarding the sarcomere and cytoskeleton of cardiomyocytes." (PMID 41214391, 2025). "To further delineate the role of CTTN-Δe11 on cardiac hypertrophy in vitro, we developed small interference RNAs to silence the expression of CTTN-Δe11 (si-Δe11) in NMCMs." (PMID 41214391, 2025). "Although our investigation identified CTTN as a key functional mediator through which RBMS1 contributes to cardiac hypertrophy, we recognize that the study has certain limitations." (PMID 41214391, 2025). "Taken together, these results demonstrate that the regulation of cardiac hypertrophy by RBMS1 is relied on the splicing of CTTN to generate CTTN-Δe11." (PMID 41214391, 2025). "Despite its emerging role in these conditions, the function of CTTN in cardiac hypertrophy remains undefined." (PMID 41214391, 2025). "In addition, we determined that the detrimental effects of RBMS1 overexpression in hypertrophy were eliminated by CTTN-Δe11 deficiency, demonstrating that the function of RBMS1 in cardiac hypertrophy depends on CTTN-Δe11." (PMID 41214391, 2025). "We identified CTTN as a downstream target of RBMS1 and hypothesized that RBMS1 regulates the organization of the sarcomere and cytoskeleton in cardiomyocytes by splicing CTTN to produce the CTTN-Δe11 isoform in cardiac hypertrophy." (PMID 41214391, 2025). "Subsequently, we assessed whether RBMS1 is involved in cardiac hypertrophy by splicing of CTTN." (PMID 41214391, 2025). "Thus, we speculated RBMS1 activated PI3K/AKT pathway through generating CTTN-Δe11 to regulated cardiac hypertrophy." (PMID 41214391, 2025). "The activated alternative splicing of CTTN regulated by RBMS1 promotes disorganization of the cardiomyocyte sarcomere via activation of the PI3K/AKT pathway, ultimately contributing to cardiac hypertrophy." (PMID 41214391, 2025). "However, the role of CTTN in cardiac hypertrophy remains unclear." (PMID 41214391, 2025). "However, in addition to CTTN, there are likely other unidentified target genes of RBMS1 that may play roles in cardiac hypertrophy via distinct biological processes or pathways." (PMID 41214391, 2025).
cardiomyopathy (1 paper, 2022). A disease of the heart muscle or myocardium proper. "A synergistic effect through α-tubulin, cortactin, ERK, and Smad signaling and autophagy induction might be highly beneficial in LMNA-cardiomyopathy." (PMID 36550158, 2022).
Cirrhosis (1 paper, 2022). A chronic disorder of the liver in which liver tissue becomes scarred and is partially replaced by regenerative nodules and fibrotic tissue resulting in loss of liver function. "We also observed that genes associated with cytoskeleton and focal adhesion, such as ACTN1 and CTTN, are up-regulated and are related to HCV-mediated cirrhosis." (PMID 36016316, 2022).
clear cell carcinomas (1 paper, 2021). "Another study also reported upregulated expression of FSCN1, cortactin, and EGFR in TMAs of four ovarian carcinomas (serous carcinoma, mucinous carcinoma, endometrioid adenocarcinoma, and clear cell carcinoma)." (PMID 34830909, 2021).
clear cell renal cell carcinoma (1 paper, 2025). "One study suggests SAMHD1 expression promotes focal adhesion kinase (FAK) signaling by binding to cortactin, and in turn activated Rac family small GTPase 1 (Rac1)-mediated lamellipodia formation in human clear cell renal cell carcinoma." (PMID 41280104, 2025).
colorectal tumors (1 paper, 2014). "Discrepancy between unaltered mRNA expression and elevated levels of total and phosphorylated cortactin excluded the possibility of gene amplification and suggested possible posttranslational modification(s) and changes in protein stability in colorectal tumors." (PMID 24465712, 2014).
dilated cardiomyopathy (1 paper, 2025). Cardiomyopathy which is characterized by dilation and contractile dysfunction of the left and right ventricles. "By combining volcano plot and GO analysis, we identified differentially expressed genes enriched in hypertrophic and dilated cardiomyopathy, including TTN, TPM3, CTTN, LAMA4, and ITGB1." (PMID 41214391, 2025).
endocrine cancer (1 paper, 2016). "This study identifies a novel interaction between proto-oncogene PBF and cortactin which opens up new therapeutic avenues for blocking tumour cell movement in endocrine cancer." (PMID 27603901, 2016). "Hence, therapeutic strategies to manipulate the PBF:CTTN interaction need to be further appraised as promising new avenues in the treatment of endocrine tumor metastasis." (PMID 27603901, 2016).
epithelial dysplasia (1 paper, 2025). "Moreover, the possible participation of cortactin in SCC carcinogenesis had been postulated in the early stages of OSCC, as its expression was significantly elevated in potentially malignant oral lesions, with higher levels observed in lesions with greater epithelial dysplasia." (PMID 40217339, 2025).
experimental autoimmune encephalomyelitis (1 paper, 2023). An autoimmune demyelinating disease of the central nervous system that is produced experimentally in animals by the injection of homogenized brain or spinal cord in Freund's adjuvant. "In another study of experimental autoimmune encephalomyelitis (EAE), cortactin knockout mice exhibited decreased incidence, disease severity, and infiltration of the central nervous system by CD4+ T cells." (PMID 37485352, 2023).
gastric diseases (1 paper, 2024). "Future investigations employing gastric organoid models and/or human gastric sections will provide further insights into the role of cortactin in H. pylori-driven gastric diseases." (PMID 38646547, 2024).
Immunodeficiency (1 paper, 2021). Failure of the immune system to protect the body adequately from infection, due to the absence or insufficiency of some component process or substance. "ABPs such as gelsolin, Tβ4, filamin, villin-1, gelsolin, profilin-1, SYNPO, and cortactin are abnormally expressed in certain inflammatory environments, where they inhibit or induce immunodeficiency inflammation." (PMID 34194957, 2021).
inflammatory bowel disease (1 paper, 2024). A spectrum of small and large bowel inflammatory diseases of unknown etiology. "On the other hand, in patients with inflammatory bowel disease (IBD), decreased cortactin levels and loss of co-localization with ZO-1 were associated with intestinal epithelial barrier dysfunction." (PMID 38646547, 2024).
influenza infection (1 paper, 2021). "These authors further identified the presence of a caspase 3 cleavage site in the actin-binding domain of CTTN and reported that CTTN degradation is associated with executionary apoptotic caspase during influenza infection." (PMID 34831092, 2021).